PKD1 (polycystin 1, transient receptor potential channel interacting)
Diseases named in the same sentence as PKD1 in open-access papers (continued):
Sharing a sentence is not in itself a finding about the gene and the disease.
cyst (continued). "For example, topoisomerase inhibitors and tubulin interference drugs were previously identified for their ability to reduce cyst growth in a large screen of ~ 8000 compounds in Pkd1-null 3D-grown cells." (PMID 37217845, 2023). "In PKD1-deficient cells, 4-HNE, as a signaling molecule, promotes cell proliferation and aggravates cyst growth by activating AKT, S6, STAT3, and RB." (PMID 37739961, 2023). "In fact, MET increased cyst growth and was toxic when administered at a later stage of the disease in Pkd1 miRNA mice." (PMID 37653564, 2023). "In summary, the loss of FPC in hypomorphic Pkd1V/V mice results in a kidney phenotype similar to the Pkd1 null condition, with cystic expansion in glomeruli, proximal tubules, and accelerated cyst growth in distal tubules and collecting ducts." (PMID 37845212, 2023). "This theory has been supported by a report of amelioration of cyst growth by suppression of AGT synthesis in PKD1 animal model." (PMID 38027263, 2023). "Nuclear translocation of Tfeb was observed before cyst formation in some cells at 1 day post-DOX from Pkd1 KO kidneys." (PMID 36794754, 2023). "For example, PKD1 inactivation in newborn mice leads to rapid cyst development, whereas ablating it after P13 leads to slowly progressive adult-onset PKD20,21." (PMID 36627370, 2023). "Two proteins encoded by PKD1 and PKD2, polycystin-1 and polycystin-2, are involved in cyst formation." (PMID 37241147, 2023). "The upregulation of MCP-1 following Pkd1 knockdown promotes the accumulation of macrophages and subsequent cyst growth through a mechanism dependent on cellular proliferation." (PMID 38239353, 2023). "In order to explore the potential contribution of MCP-1 and macrophages in facilitating cyst expansion, a study was conducted where Pkd1 knockout alone (single knockout) or both Pkd1 and MCP-1 were knocked out in mouse renal tubules." (PMID 38239353, 2023). "This mosaic feature of cyst-lining cells is in agreement with previous rodent models of Tsc1 and PKD1/2 inactivation." (PMID 36627370, 2023). "The H+-ATPase expression in Pkd1 mice is shown for comparison and indicates a completely different pattern, with few cells lining the cysts expressing H+-ATPase, whereas labeling with AQP-2 is very robust in cyst epithelia in Pkd1 mutant mice." (PMID 38028758, 2023). "In contrast to EGF and growth factor expression, the upregulation of Mcp1 precedes macrophage infiltration and promotes macrophage accumulation and cyst growth in Pkd1-knock-out mouse models." (PMID 36342644, 2023). "Cystic cell derived extracellular vesicles (EVs) and urinary exosomes derived from ADPKD patients promoted cyst growth in Pkd1 mutant kidneys and in 3D cultures." (PMID 36203940, 2022). "Cyst-lining epithelial cells of the cyst walls showed mixed populations of cells with prominent and faint PKD1 signals." (PMID 34980882, 2022). "Two STAT3 inhibitors, pyrimethamine and S3I-201, also inhibited cyst growth in a neonatal and an adult Pkd1 model." (PMID 36120538, 2022). "The other ADPKD gene, PKD2, also contains a 3′-UTR miR-17 binding motif; remarkably, deleting this miR-17 motif increases Polycystin-2 (PC2) levels and attenuates cyst growth in Pkd1-mutant models." (PMID 35965273, 2022). "Inhibition of DNA methylation with 5-aza-2′-deoxycytidine increased the expression of Pkd1 and decreased the cyst formation of MDCK cells." (PMID 36120538, 2022). "After that day, increased numbers of CD cells showed highly proliferative and fibrotic characteristics, as detected in later-stage Pkd1 homozygous kidneys, both of which should contribute to cyst growth and renal fibrosis." (PMID 36611841, 2022). "Considering the available evidence on the role of EVs on cyst progression, our findings demonstrating the increased EV release by Pkd1-/- DCT cells support a role of this segment in ADPKD pathogenesis." (PMID 36299464, 2022).
cyst (continued). "Immunostaining using an anti-PKD1 antibody revealed a PKD1-positive signal in the epithelial cells of the cyst wall." (PMID 34980882, 2022). "Tulp3 deletion caused polycystic kidney disease that was intermediate between Pkd1 deletion and cilia deletion, implying that trafficking to cilia is a critical factor in the ability of polycystins to prevent cyst formation." (PMID 35253003, 2022). "A significant reduction (44.7%) in the number of BrdU-labeled cyst-lining cells was detected in Pkd1-miR Tg mice with suramin treatment compared with the saline-treated group (p < 0.01)." (PMID 35955634, 2022). "In previous studies, we have generated the PKD1+/− pigs to simulate the progression of cyst formation and physiological alterations similar to those seen in ADPKD patients." (PMID 36309681, 2022). "Macrophage migration inhibitory factor (MIF) reported to be upregulated in cyst-lining epithelial cells of Pkd1 mutant mouse kidneys, accumulates in cyst fluid of human ADPKD kidneys." (PMID 35847973, 2022). "We examined the effect of suramin on cyst progression in a Pkd1 microRNAs transgenic mouse model that presented stable Pkd1 knockdown and moderate disease progression." (PMID 35955634, 2022). "Here, inactivation of Pkd1 before P13 resulted in severely cystic kidneys within 3 weeks (early onset [EO]), whereas inactivation at day 14 and later resulted in cyst development only after 5 months (late onset [LO])." (PMID 36326820, 2022). "We further investigated the potential of H2-GMZ to target cyst formation and enlargement in a mouse metanephric organ culture model and in vivo in a polycystin-1 (Pkd1) conditional mouse." (PMID 35979967, 2022). "EZH2 is upregulated in cystic renal epithelial cells, the targeting of which delayed cyst growth in Pkd1 knockout mouse models." (PMID 35865176, 2022). "Along with cyst initiation, PKD1 inhibition unleashes large-scale transcriptomic and metabolic dysregulation and activates numerous oncogenic pathways, such as cAMP and c-Myc/Yap4,37–45." (PMID 35965273, 2022). "Treatment with the mitochondrion-specific antioxidant MitoQ reduced mitochondrial superoxide production and proliferation of cyst-derived PKD1 heterozygous cells." (PMID 36120538, 2022). "If TULP3/IFT-A can traffic the components for both CLCI and cCDCA signals to cilia in the absence of polycystins, why does concomitant Tulp3 cko result in such different effects on cyst growth following early and late Pkd1 gene inactivation?" (PMID 35832738, 2022). "The conclusion from this analysis is supported by our recent study, which found that MIF played an important role in regulating different signaling pathways, and the inhibition of MIF delays cyst growth in Pkd1 mutant mice." (PMID 36611841, 2022). "An alternative parsimonious interpretation would be that persistent cyst growth in Pkd1-cilia double mutants arises from additional ciliary roles independent of polycystins." (PMID 35832738, 2022). "Second, cyst growth continues to persist in Pkd1-cilia double mutants; however, loss of cilia should prevent CDCA from initiating cystogenesis if the cyst activation signal solely originates in the cilium." (PMID 35832738, 2022). "It has been reported that postnatal day 14 is a critical time point for determining cyst development in Pkd1 conditional knockout mouse kidneys." (PMID 36611841, 2022). "Remarkably, Pkd2 is also inhibited via its 3′-UTR miR-17 motif, and Pkd2∆17-induced Polycystin-2 derepression retards cyst growth in Pkd1-mutant models." (PMID 35965273, 2022). "Another important result of our scRNA-seq analysis was the identification of changes in gene expression in cells adjacent to Pkd1 mutant collecting duct cells, including in macrophages, T cells, and fibroblasts during cyst initiation and progression." (PMID 36611841, 2022).
cyst (continued). "In this context, the Nishinkamura laboratory recently reported the use of PKD1 mutant hiPSCs to generate UB organoids with cyst forming capacity providing a robust in vitro ADPKD model." (PMID 36120564, 2022). "The additional stimuli, called the third hit, was proposed when it was found that deletions of Pkd1 or Ift88 in mice with fully developed kidneys were largely immune to cyst formation unless they incurred kidney injury." (PMID 35253003, 2022). "The concomitant ablation of cilia significantly suppressed rapid cyst growth in Pkd1 cko compared with Pkd1 cko single mutants." (PMID 35832738, 2022). "This cluster was stated to modulate the cystic growth in the kidney by triggering cyst epithelial proliferation and inhibiting the post-transcriptional expression of PKD1, PKD2, and hepatocyte nuclear factor 1β (HNF-1β)." (PMID 35205236, 2022). "The Pkd1 cko late-onset model offers a cyst suppressor system to test the cCDCA candidates from among the TULP3/IFT-A ciliary cargoes." (PMID 35832738, 2022). "Eliminating this motif (Pkd1∆17) improves mRNA stability, raises Polycystin-1 levels, and alleviates cyst growth in cellular, ex vivo, and mouse PKD models." (PMID 35965273, 2022). "In this study, we determined the effects of suramin on cyst growth and disease progression in an established Pkd1 hypomorphic model of ADPKD." (PMID 35955634, 2022). "We quantified the cystic area from those micrographs using ImageJ software, and as shown in Figure 4Aii, there was a dramatic increase in cyst size in the Pkd1-null cells (PN24) as compared to the Pkd1+/− heterozygous cells under cyst-inducing conditions." (PMID 36504724, 2022). "The investigators inferred that 109 of these compounds reduced cyst growth in Pkd1−/− cells cultured in a 3D matrix." (PMID 34901057, 2021). "We show that cystic cell derived extracellular vesicles and urinary exosomes derived from ADPKD patients promote cyst growth in Pkd1 mutant kidneys and in 3D cultures." (PMID 34315885, 2021). "To further investigate the effect of mCAT treatment on cyst progression in kidneys of PKD1 mutant mice, we performed a pathological examination." (PMID 34671066, 2021). "This miRNA drives cyst epithelial proliferation and inhibits the post-transcriptional expression of Pkd1, Pkd2, and hepatocyte nuclear factor 1β (Hnf-1β)." (PMID 34901057, 2021). "We investigated the flow-dependent PT transport in 3 major polycystic kidney disease (PKD) and ciliopathy animal models of Pkd1-, Pkd2-, and Kif3a-KO mice after gene KO but prior to cyst formation." (PMID 33886508, 2021). "In contrast, inhibition of Hh signaling using GLI and SMO small molecule antagonists Gant61 and Sant2 respectively prevented cyst formation in kidney explants from Ttc21b/Ift139-conditional knockout, jck/Nek8/Nphp9 and Pkd1 mutant mice." (PMID 34055783, 2021). "Six weeks after the inactivation of Pkd1 gene, coincident with the onset of cyst development, male mice were randomly divided into 2 subgroups receiving SR59230A (4 mg/kg) via i.p. injection every 24 h for 4 weeks or vehicle alone (DMSO <4%)." (PMID 34676684, 2021). "Given the robust evidence of altered cystogenic characteristics of cystic cell-derived EVs/exosomes and ADPKD urinary exosomes in vitro, we investigated if treatment with Pkd1-null cell EVs/exosomes promotes cyst growth in vivo." (PMID 34315885, 2021). "Demethylation of an immortalised cell line (WT 9–12) resulted in increased PKD1 mRNA expression, and treatment of the cyst-forming cell line MDCK with a DNMT inhibitor repressed the growth of cysts." (PMID 34948126, 2021).
cyst (continued). "Previous studies have demonstrated the inhibitory effect of curcumin on cyst growth by inhibiting cell proliferation and promoting epithelial cell differentiation in Pkd1 deletion mouse models, suggesting its potential to be a natural candidate drug for ADPKD." (PMID 33986666, 2021). "ADPKD is caused by mutations in the PKD1 and PKD2 genes, coding for polycystin-1 (PC1) and polycystin-2 (PC2), respectively, resulting in cilia alterations and cyst formation." (PMID 34339420, 2021). "Two male patients aged 7.7 and 9.3 years had genetically confirmed contagious genes syndrome (deletion involving TSC2 and PKD1 genes) with very large renal cysts (maximal cyst diameter −35 and 44 mm, respectively)." (PMID 34912759, 2021). "In Pkd1 and Pkd2 knock out mice, miR-21 also targets tumor suppressor programmed cell death 4 (Pdcd4) mRNA to stimulate cyst formation." (PMID 33920158, 2021). "Here, we demonstrate that hypoxia-inducible transcription factor (HIF) 1α upregulates MIF in cyst-lining cells in a tubule-specific PKD1 knockout mouse." (PMID 32885302, 2020). "Induction of cyst formation by downregulation of Pkd1 (Pkd1−/−) is paralleled by upregulation of TMEM16A expression." (PMID 32859916, 2020). "We first tested the efficacy of a second ROCK inhibitor, hydroxyfasudil, in 3D cyst assays using a patient-derived PKD1 cystic line (OX161)." (PMID 32663194, 2020). "Here, we established ADPKD patient‐specific iPSCs to study the function of PKD1 in kidney development and cyst formation in vitro." (PMID 32163234, 2020). "Our results suggest a scenario in ADPKD in which DNA damage results in increased oxidative stress, and oxidative stress increases the expression of p68 to further inhibit the expression of PKD1 and promote cyst growth." (PMID 32724471, 2020). "We found that 109 of these compounds also reduced in vitro cyst growth of Pkd1-null cells cultured in a 3D matrix." (PMID 32144367, 2020). "While inhibition of apoptosis has been shown to delay renal cyst growth in some animal models of PKD, induction of apoptosis of cyst-lining epithelial cells has been shown to slow disease progression in Pkd1 knockout mice." (PMID 32885302, 2020). "In the adult kidney, the exact function of PKD1 is unclear, but it is required in the renal epithelium to prevent cyst formation." (PMID 32163234, 2020). "They used embryonic kidney cultures of wild-type mice in which 8-Br-cAMP was employed to initiate cyst-formation combined with an in vivo approach based on a Pkd1 kidney-specific knock-out strain." (PMID 32630605, 2020). "Additional stimulation with forskolin further augments cyst size which is more distinct in Pkd1−/− than in Pkd1+/+ cysts." (PMID 32859916, 2020). "The present study has generated induced pluripotent stem cells (iPSCs) of ADPKD patients to study the function of PKD1 in kidney development and cyst formation in vitro." (PMID 32163234, 2020). "Disease causing mutations in Polycystin-1 (PKD1; ~85% of cases) and Polycystin-2 (PKD2; ~15% of cases) are known, but the complex mechanisms for cyst development and cyst growth are still poorly understood." (PMID 32859916, 2020). "Here we demonstrate that loss of Pkd1 increased expression of TMEM16A and CFTR and Cl− secretion in murine kidneys, with TMEM16A essentially contributing to cyst growth." (PMID 32859916, 2020). "In support of our findings, it has been recently reported that ROCK inhibitors and DNA methylation inhibitors decrease cyst formation in 3D cultures of PKD1 mutant mIMCD3 cells and canine kidney cells, respectively." (PMID 32144367, 2020). "Mutations of one or more PKD genes, including PKD1 (in 78% of disease pedigrees), PKD2 (in 13% of disease pedigrees) and GANAB (in ~0.3% of disease pedigrees) result in cyst formation." (PMID 32724471, 2020). "Immunolabelling of TMEM16A and CFTR indicate upregulation of both ion channels in the cyst epithelium of Pkd1−/− kidneys, where both ion channels are strongly colocalized." (PMID 32859916, 2020).
cyst (continued). "Positive hits (both enhancers and repressors) were then confirmed in 3D cyst assays using two cell lines, one being a well characterised human PKD1 patient-derived cystic cell line." (PMID 31919453, 2020). "Our immunostaining analysis further indicated that p68 was elevated in DBA, a collecting duct marker, positive cyst lining epithelia in Pkd1 conditional knockout mouse kidneys and human ADPKD kidneys but not in wild type (WT) and normal human kidneys." (PMID 32724471, 2020). "In support of the potential repurposing of known ROCK inhibitors, one study demonstrated rescue of cord and tubule formation whilst reducing cyst formation in the cystogenic Pkd1 knock-out 3D kidney cell-line model." (PMID 33392209, 2020). "We also found that p68 was upregulated in Pkd1 mutant renal epithelial cells and cyst lining epithelial cells in Pkd1 knockout mouse kidneys and ADPKD patient kidneys." (PMID 32724471, 2020). "In vitro, 3D culture of Yap KO or Yap/Pkd1 KO renal epithelial cells resulted in abnormal cyst formation, with only sporadic lumen formation and development of tumour‐like structures." (PMID 32592332, 2020). "ADPKD is caused by mutations in PKD1 (polycystin 1) or PKD2 (polycystin 2), but the underlying complex molecular events leading to continuous cyst growth are still poorly understood." (PMID 32185407, 2020). "The genetic mechanisms that are known focus on mutations in the genetic drivers polycystin-1 (PKD1) and polycystin-2 (PKD2) that result in cyst formation once a certain threshold of insufficient protein product is reached." (PMID 33022986, 2020). "Remarkably, we found several somatic mutations in genes other than PKD1 or PKD2, ranging from 3 to 15 mutations per cyst." (PMID 32163234, 2020). "In conclusion, we show that cyst progression and fibrosis in Pkd1/Fjx1 double KO mice are partially uncoupled and demonstrate a new, yet undefined, role of Fjx1 in fibrosis, ultimately resulting in longer survival." (PMID 31038742, 2019). "In a previous study, we demonstrated that renal injury can accelerate cyst formation in Pkd1 knock‐out (KO) mice." (PMID 31038742, 2019). "In this study, we first show genetic inactivation of Hdac5 can suppress cyst formation in Pkd1–/–mice." (PMID 31059522, 2019). "We showed previously that upon nephrotoxic injury cyst initiation is faster in mice with Pkd1 deletion compared with the non‐injured group 8." (PMID 31038742, 2019). "ADPKD is caused by mutations in either PKD1 or PKD2 genes, where disruption of their normal functions leads to excessive proliferation of the renal tubular epithelium causing cyst formation." (PMID 31515477, 2019). "Recently, advances in human kidney organoid research enabled the generation of PKD1-null cyst formation in vitro." (PMID 31822676, 2019). "In our study, Fjx1 showed aberrant expression during both the injury‐repair phase and cyst progression in Pkd1 KO mice compared with WT mice." (PMID 31038742, 2019). "We further investigated the mechanism by which dopamine receptor antagonists promotes HDAC5 nuclear export and demonstrated the ability of one of these compounds to slow cyst growth in Pkd1–/–mice." (PMID 31059522, 2019). "Both loss of Lkb1 and Pkd1 render cells dependent on glutamine for growth and inhibition of glutamine metabolism in both Lkb1/Tsc1 and Pkd1 mutant mice significantly reduces cyst progression." (PMID 31336917, 2019). "We found that mice that are double KO for Fjx1 and Pkd1 display cyst formation comparable to that of single Pkd1 KO mice but survive longer." (PMID 31038742, 2019). "The cells lining the cysts in Pkd1 mice showed a relative increase in the number of PCNA‐positive cells in cyst epithelium as compared to wild‐type mice (fourth panel)." (PMID 30675765, 2019). "As in humans and mice, near-complete PKD1 depletion induces severe cyst formation mainly in collecting ducts." (PMID 31822676, 2019).